KEAP1 (kelch like ECH associated protein 1)
Diseases named in the same sentence as KEAP1 in open-access papers (continued):
Sharing a sentence is not in itself a finding about the gene and the disease.
cardiovascular diseases (21 papers, 2016 to 2026). "In the intersected Group B, 765 DEGs co-regulated in both Keap1−/− and Keap1-Restored cell lines were also associated with cardiovascular disease, signal transduction, biological adhesion, metabolic process, and cellular process." (PMID 36142252, 2022). "At present, p62/Keap1/Nrf2 targeting system and its related pathways (such as autophagy) are potential strategies for the treatment of cardiovascular diseases." (PMID 37063954, 2023). "By interacting with Keap1/Nrf2, which plays an important role in regulating oxidative stress, while p62 is participated in cell survival, growth and death in cardiovascular diseases." (PMID 37063954, 2023). "The capacity of MFAEs to activate Keap1/Nrf2 signaling has also been validated in other pathological conditions (for example, alcohol-induced liver damage, cardiovascular disease, and antioxidant disorders." (PMID 37032323, 2023). "In summary, several studies suggest that Nrf2 and autophagy can, in tandem, suppress the development of cardiovascular diseases, particularly through the p62/Keap1/Nrf2 feedback loop and by reducing free radicals levels." (PMID 35406767, 2022). "Modulation of Nrf2/Keap1/HO-1 signaling treats cardiovascular diseases by alleviating oxidative stress in cardiomyocytes, enhancing the cellular antioxidant defense system, and upregulating the viability of cardiomyocytes." (PMID 33312223, 2020). "The Keap1-Nrf2-ARE signaling system can prevent cardiovascular disease (CVD) by preventing smoldering inflammation." (PMID 28933413, 2016). "Therefore, the Keap1/Nrf2 pathway is also considered one of the most important pathways in OS, which is involved in the treatment of cardiovascular disorders, nervous system disorders, tumors, and other diseases." (PMID 38733688, 2024). "It was confirmed that Nrf2/Keap1 signaling pathway could be activated to regulate protective effect against cardiovascular disease." (PMID 29448942, 2018). "Therefore, Tsg101 may be a targeted drug for the treatment of cardiovascular diseases through the p62/Keap1/Nrf2 pathway." (PMID 37063954, 2023).
kidney disease (19 papers, 2012 to 2025). "Other drugs involved in molecular targeting influence important pathways implicated in kidney disease progression, such as the KEAP1-Nrf2 axis and the UPS." (PMID 40149885, 2025). "Although further studies, such as the relationship between the effect of Nrf2 activation and its threshold in each kidney disease model, are required, future clinical application of Keap1-Nrf2 PPI inhibitor to CKD is expected." (PMID 40527586, 2025). "In mouse models of ischemia and unilateral ureteral obstruction, KEAP1 hypomorphic mice displayed attenuated kidney disease compared to KEAP1-intact mice." (PMID 33477669, 2021). "In this review, we introduce the molecular functions of Keap1 and Nrf2 in kidney disease as well as up-to-date information on the development of drugs targeting the Keap1–Nrf2 system for kidney disease treatment." (PMID 32331329, 2020). "Numerous studies using genetically modified animals (e.g., Nrf2 knockout animals, Keap1 knockdown animals) have reported the relation between Nrf2 and kidney disease." (PMID 32594372, 2020). "For the first time in kidney disease, we describe the use of Keap1 hypomorphic mice, which possess Nrf2 hyperactivation." (PMID 27804998, 2016). "The Keap1/Nrf2 pathway is a master regulator of antioxidant, anti-inflammatory, and other cytoprotective mechanisms important in protection from kidney disease." (PMID 27804998, 2016). "The Keap1/Nrf2 pathway is a master regulator of cytoprotective genes and a promising target for therapeutic intervention in kidney disease." (PMID 27804998, 2016). "•The development of Keap1-Nrf2 PPI inhibitors may create treatment options for kidney diseases with reduced off-target effects." (PMID 31279986, 2019). "Directly disrupting the Keap1-Nrf2 complex can activate the protein levels of Nrf2 and thereby provide a cell protection mechanism against oxidative assault when endogenous stress defence mechanisms are imbalanced, which could be part of critical therapies for kidney diseases." (PMID 31279986, 2019). "In contrast, mild Nrf2 activation by genetic Keap1 knockdown (KD) or rodent tolerable bardoxolone methyl analog, CDDO-imidazolide (CDDO-Im), did not attenuate kidney disease progression in Alport mice, suggesting that strong Nrf2 activation is essential for clear therapeutic efficacy." (PMID 40527586, 2025).
neurological diseases (13 papers, 2019 to 2025). "Previous research demonstrated that oxidative stress is implicated in most neurological diseases and that the Keap1-Nrf2 cascade has the potential to defend against oxidative damage." (PMID 38664646, 2024). "The Keap1-Nrf2/HO-1 cascade is also implicated in various processes, such as mitophagy and cell apoptosis, thereby offering neuroprotection against several nervous system diseases." (PMID 38664646, 2024). "In recent years, the role of the Kelch-like ECH-associated protein 1 (Keap1)/Nuclear factor-erythroid 2-related factor 2 (Nrf2) signaling pathway in nervous system disorders has received extensive clinical attention." (PMID 38733688, 2024). "Kelch-like ECH-associated protein 1 (Keap1)-nuclear factor-erythroid 2-related factor 2 (Nrf2) signaling pathway is considered a critical defense mechanism to protect the body from oxidative stress in nervous system disorders." (PMID 36950126, 2023). "Several research studies on nitrosative/oxidative stress or inflammatory response in neurological diseases have suggested the critical role of the antioxidant pathway involving the Kelch-like ECH-associated protein (Keap1)/nuclear factor erythroid 2-like 2 (NFE2L2, namely Nrf2)." (PMID 34122094, 2021). "As confirmed in various neurological disease models both in vivo and in vitro, the Keap1-Nrf2-ARE pathway exerts neuroprotective effects by increasing astrocytes’ glutathione secretion." (PMID 40289983, 2025). "Oxidative stress and Nrf2 activators can trigger Nrf2 activation by releasing Nrf2 from KEAP1 and allowing Nrf2 to translocate into the nucleus, where it activates the expressions of antioxidant enzymes to eliminate ROS and facilitate neuronal survival in many neurological diseases." (PMID 37239873, 2023).
metabolic disease (8 papers, 2014 to 2025). A congenital disorder (due to inherited enzyme abnormality) or acquired (due to failure of a metabolically important organ) disorder resulting from an abnormal metabolic process. "The latest studies suggest that lower activity of the Nrf2-Keap1 system (“nuclear factor-erythroid-2-related factor 2” and “kelch-like ECH-associated protein 1”) is also associated with metabolic disease’s development." (PMID 37372020, 2023). "PMQ exhibited potent protective effects on metabolic disorders and cardiac remodeling, which were associated with its effect of enhancing the endogenous antioxidant function through the activation of sestrins/Keap1/Nrf2 signaling." (PMID 32090078, 2020). "In order to assess the pharmacological potential of hepatic Nrf2 activation in metabolic disease, Nrf2 was activated over 7 weeks in mice on Western diet using two different siRNAs against kelch-like ECH-associated protein 1 (Keap1), the inhibitory protein of Nrf2." (PMID 27814396, 2016). "The unchanged GPx levels observed in all the groups with PCOS and only slightly reduced GR in the groups with increased risk of metabolic disorders may be the result of a compensatory antioxidant response associated with the activation of the Keap1-Nrf2 system." (PMID 36978978, 2023). "Numerous studies have demonstrated therapeutic benefit of KEAP1-targeting compounds in multiple experimental models of chronic disease, including respiratory, gastrointestinal, cardiovascular, neurodegenerative, autoimmune, and metabolic diseases." (PMID 32424161, 2020). "Therefore, the implication of Nrf2 in hormonal and metabolic diseases warrants further investigations considering that the Keap1-Nrf2-ARE pathway is now moving into the realm of drug development." (PMID 25014534, 2014). "Notably, CP and OP effectively prolonged the lifespan of fruit flies, rescued locomotor depression and metabolic disorder, improved intestinal morphology, and protected the integrity of the intestinal barrier by inhibiting the JAK/STAT pathway and enhancing the Nrf2/Keap1 pathway." (PMID 40431477, 2025).
colorectal (7 papers, 2010 to 2025). "Adoptive transfer of AKT- or MST1-overexpressing macrophages, or Keap1 disruption in myeloid-specific TSC1-knockout mice promoted NRF2 activation but reduced TLR4 activity and mitigated I/R-induced liver inflammation." (PMID 38360839, 2024).
bacterial infection (4 papers, 2021 to 2024). "The altered responses were reversed by treatment with Nrf2 agonists such as sulforaphane and compound 7, capable of rescuing ME1 expression, thus demonstrating that this enzyme can become a new therapeutic target against these bacterial infections through Keap1-Nrf2 PPI inhibitors." (PMID 39763664, 2024). "Furthermore, we describe Nrf2/Keap1/AREs, PI3K/Akt/mTOR, and TLR signaling as the main signal transduction pathways of oxidative stress during bacterial infections." (PMID 34746124, 2021).
respiratory diseases (4 papers, 2020 to 2024). "Until now, several studies have identified changes in the nuclear factor-E2-related transcription factor 2 (Nrf2)-Keap1 signaling in models of respiratory diseases." (PMID 36829786, 2023). "Since oxidative stress has been closely related to human respiratory diseases, antioxidant systems, including Keap1-Nrf2, have been become an important therapeutic target for various respiratory diseases." (PMID 34445113, 2021). "Oxide-containing atmospheric environment generally contributes to the development of respiratory diseases, possibly leading to the failure of the Keap1-Nrf2 pathway." (PMID 34445113, 2021). "Therefore, this review discusses the role of the Keap1-Nrf2 signaling pathway, an antioxidative defense system, in various respiratory diseases." (PMID 34445113, 2021). "These trials to regulate the Keap1-Nrf2 pathway could potentially be developed into therapies for various respiratory diseases." (PMID 34445113, 2021). "Thus, this review describes how the expression of Keap1-Nrf2 functions in different respiratory diseases and explains the protective effects of reversing this expression." (PMID 34445113, 2021).
retinopathy (4 papers, 2017 to 2022). "The MDA level and OSI were significantly higher in Keap1 CC genotype of neuropathic patients than patients with retinopathy." (PMID 34861061, 2022). "The minor Keap1 A allele was significantly more frequent in T2DM with retinopathy than T2DM patients without complication and controls." (PMID 34861061, 2022). "Higher frequency of A allele of Keap1 (10%) was found in T2DM patients with retinopathy compared to T2DM patients without complication (4.5%, p = 0.034, OR = 2.36) and controls (4%, p = 0.019, OR = 2.67)." (PMID 34861061, 2022). "According to manifold studies, the Nrf2-Keap1 pathway is able to give an impulse to system Xc–, enhancing the resistibility of ferroptosis via Nrf2 overexpression or Keap1 drawdown, which was further confirmed to occur in the development of retinopathy in Type 1 diabetes (T1DM)." (PMID 34307381, 2021).
liver (3 papers, 2018 to 2025).
cardiac disease (1 paper, 2016). "In the heart, sustained activation of the Nrf2 pathway via Keap1 sequestration into mutant αB-crystallin aggregates leads to reductive stress, a shift of the cellular redox potential to a more reduced state that is both necessary and sufficient for development of fatal cardiac disease." (PMID 27799074, 2016).
inflammatory myopathy (1 paper, 2016). "To expand our findings to a broader spectrum of human AVMs, we performed Keap1 immunohistochemistry on FFPE tissue from subjects with IBM, a treatment-resistant inflammatory myopathy that shows evidence of autophagy dysregulation." (PMID 27799074, 2016).
reproductive disease (1 paper, 2018). "Many signaling pathways involved in female reproduction, including the Keap1-Nrf2, NF-κB, FOXO and MAPK pathways, which are affected by OS, are described, providing new ideas for the mechanism of reproductive diseases." (PMID 30126412, 2018).
skin disorder (1 paper, 2025). Any deviation from the normal structure or function of the skin or subcutaneous tissue that is manifested by a characteristic set of symptoms and signs. "Moreover, inhibition of oxidative stress has been identified as a key mechanism in UVB therapy for various skin disorders, particularly through activation of the NRF2/KEAP1 antioxidant pathway." (PMID 41200164, 2025).
KEAP1 also shares sentences with these, for which no sentence is quoted: Anxiety (8 papers); acute lung injury (7); hypothyroidism (4); Parkinson's (4); subarachnoid hemorrhage (4); alcohol (3); hyperlipidemia (3); kidney injury (3); neurotoxicity (3); psychiatric diseases (3); spinal cord injury (3); acute respiratory distress syndrome (2); bronchopulmonary dysplasia (2); chronic hepatitis B (2); colon adenocarcinoma (2); colorectal adenocarcinoma (2); coronary artery disorder (2); fetal growth restriction (2); hematologic malignancies (2); Hepatitis (2); idiopathic pulmonary fibrosis (2); infectious (2); insulinoma (2); intestinal diseases (2); intracerebral hemorrhage (2); multiple myeloma (2); Myelodysplasia (2); renal failure (2); sarcopenia (2); Serous Ovarian Cancer (2).
A further 98 diseases each share a sentence with KEAP1 in 2 papers or fewer.